MIR6769B (microRNA 6769b)
Synonyms: hsa-mir-6769b
Gene: MicroRNA gene on chromosome 1 (206,474,803 to 206,474,864, forward strand). Ensembl gene ENSG00000278465.
Homologues: Orthologues: chimpanzee MIR6769B (100% identical).